IL4 (interleukin 4)
Diseases named in the same sentence as IL4 in open-access papers (continued):
Sharing a sentence is not in itself a finding about the gene and the disease.
helminth infection (continued). "Helminth infections strongly induce Th2-skewed responses associated with cytokines (e.g., IL-4, IL-5, and IL-13), mastocytosis, eosinophilia, and antibody class-switching producing IgE [reviewed in Ref." (PMID 29670630, 2018). "Th2 associated cytokines including IL-4 and IL-13 are upregulated in both helminth infections and allergic disorders." (PMID 28494800, 2017). "More broadly IL-4 or IL-4 receptor deficiency confers susceptibility on resistant murine strains for a range of helminth infections." (PMID 25319331, 2014). "IL-4 deficient mice show a marked delay in the clearance of helminth infection and over-expression of IL-4 drives local allergic inflammation." (PMID 23991011, 2013). "Mice genetically deficient in IL4 or the IL4 receptor display impaired capacity to control experimental worm infection." (PMID 20649995, 2010). "Induction of goblet cell hyperplasia is associated with TH2 immune responses, which in helminth infections are controlled primarily by IL-13, and also IL-4." (PMID 18373844, 2008). "However, the three sites displayed similar features associated with IL-4 signaling in worm infections, such as the strong outgrowth of B cells and the expansion of VM CD8+ T cells." (PMID 40092986, 2025). "Worm-resistant domestic sheep have an upregulated IL-4 response when compared to susceptible sheep and similarly, IL-13 and IL-5, two other Th2-associated cytokines, have been negatively associated with worm infections in humans." (PMID 39963298, 2025). "In helminth infections, this axis is crucial for Th2 responses, as was demonstrated in Schistosoma mansoni-infected Ccr2-deficient mice, which exhibited defective monocytes and macrophages, and reduced IL-4 production." (PMID 40872306, 2025). "On the other hand, the upregulation of GATA3 and IL-4 might suggest a concurrent Th2 response, which is typically associated with helminth infections and allergic reactions and may contribute to the modulation of Th1/Th17 inflammatory reactions." (PMID 39339863, 2024). "The association found between the higher mean concentrations of IL-4 and nausea might be due to the underlying intestinal helminth infections." (PMID 37111135, 2023). "However, one has to keep in mind that systemic modulation of IL-4 as well as IL-13 signaling can also cause severe side-effects like a propensity towards helminth infections or acute gastric mucosal injury." (PMID 33450900, 2021). "Furthermore, worm infections have been associated with a reduced progression of colitis through the increase of IL-4/IL-13 and the upregulation of AAM." (PMID 28951733, 2017). "If similar patterns are found in other natural study systems, the analyses of IL4 promoter SNPs could provide an efficient scoring system for susceptibility to helminth infections." (PMID 21501512, 2011). "Polarized Th-2 immune activation associated with helminthic infection modifies cytokine profiles, whereby anti-inflammatory IL-4, IL-10 and IL-13 protect vessel walls from oxidized LDL-induced monocyte injury in the endothelium, and downregulate fibrinogen synthesis." (PMID 19668697, 2009). "Helminth infection was associated with elevated type 2 immune responses including increased eosinophil numbers in the mesenteric lymph nodes, liver and adipose tissues, as well as increased expression of IL-4 and alternatively activated macrophage marker genes in adipose tissue, liver and gut." (PMID 33613446, 2020). "Typically, chronic helminth infections are associated with the induction of a biased Th2associated immune response, although the response to schistosome parasites prior toegg-laying is thought to comprise a mixed Th1/Th2 phenotype with IFNγ productionalongside IL-4 and IL-5." (PMID 21445234, 2011). "During helminth infection, interleukin-13 (IL-13) or IL-4 drive a 10-fold expansion of tuft cells to promote helminth clearance." (PMID 41739917, 2026).
helminth infection (continued). "Another study showed that elevated IL-4 presence during helminth infections results in the expansion of an IL4-induced naïve CD4+ T cell cluster, and these naïve CD4+ T cells are biased towards a hyporesponsive state upon alum treatment." (PMID 39866877, 2025). "In helminth infections, antigen proteins activate Th2 to stimulate the secretion of IL-4 and IL-13, which will stimulate the secretion of Tregs and IL-10." (PMID 41239264, 2025). "Typically, worm infections increase Th2 cytokines, such as IL-4 and IL-13, while decreasing Th1 cytokines like IL-12 and IFN-γ." (PMID 41268546, 2025). "In the context of helminth infections, Lck has also been identified as an immunomodulator of the immune system by promoting the T-helper-2 immune response characterized by the secretion IL-4, IL-5 and IL-13." (PMID 40725160, 2025). "In the gut, their classical role was attributed to protection against parasitic infections—a notion supported by the Th2-dominated responses (IL-4, IL-5, IL-13) and elevated eosinophil counts observed in helminthiasis." (PMID 40860650, 2025). "A study in 2012 showed that TFH cell-derived IL-4 is a key factor for inducing IgE production in a mouse model of worm infection." (PMID 40027134, 2025). "In helminth infections, the immune response is predominantly skewed toward a Th2 profile, characterized by the activation of IL-4, IL-5, and IL-13 pathways, increased eosinophil recruitment, and IgE class-switching." (PMID 41227415, 2025). "Helminth infection engages IL-4/IL-13–STAT6 signaling to tune intestinal epithelial glucose transport, thereby rebalancing luminal handling and dampening nutrient-driven inflammation." (PMID 41268546, 2025). "The mammalian mannose receptor (CD206) is expressed by several types of tissue macrophages and is considered an M2 macrophage marker as its expression is promoted by IL-4 and increased during helminth infections." (PMID 39140728, 2024). "This is different when we compare it with other helminth infections; for example, during schistosomiasis, IL-4/IL-13, specifically produced by Th2-CD4+ cells, was associated with protection." (PMID 38392907, 2024). "Similar mixed expression was observed with macrophages stimulated with LPS/IL-4; also, it is widely recognized that helminth infections can induce a dual M1/M2 profile." (PMID 38392907, 2024). "In contrast to Salmonella, helminth infections typically induce a modified, IL-4-driven type 2 immune response characterized by Th2 and Treg cells which can impair immunity to bacterial and viral infections." (PMID 39140728, 2024). "Conversely, Th2 cells and their signature cytokines (IL-4, IL-5, and IL-13) are largely characterized by their role in helminth infection or allergic responses and the promotion of IgE-mediated eosinophilic responses." (PMID 38672668, 2024). "The large extracellular helminth infection induces a strong, modified Th2 characterised by the production of cytokines such as interleukin-4 (IL-4), IL-5, and IL-13." (PMID 39057051, 2024). "Inducing tuft cell hyperplasia with helminth infection or only recombinant IL-4 or IL-25 thus supports MNV CR6 replication." (PMID 38277692, 2024). "Studies measuring macrophage activity through IL4/IL13 have demonstrated their anti-inflammatory function in regulating helminth infections." (PMID 39057830, 2024). "Helminth infections induce IL-4 production and Heligomosomoides polygyrus (H. polygyrus) infection can also induce the accumulation of IL-4 activated TRMs in the peritoneal cavity." (PMID 38712032, 2024). "Intestinal MC recruitment and activation in mice during both gastrointestinal helminth infection and malaria are marked by MC responsiveness to IL-4, with activated MCs relocating to the villus and returning to the crypts after infection resolution." (PMID 38780542, 2024). "During helminth infections, eosinophils support type 2 immunity by secreting IL-4, IL-5, IL-10, and IL-13." (PMID 39140728, 2024).
helminth infection (continued). "The administration of IL-4 from an external source can effectively treat persistent worm infections, whereas the use of IL-4 antagonists hinders the protective responses against such infections." (PMID 38251210, 2024). "Another source of IL-4, essential to generating M2 macrophages during helminth infections, is the T-CD4+ lymphocyte, where the synergy between T cells and group 2 innate lymphoid cells (ILC2) for IL-13 production has been described." (PMID 38392907, 2024). "Here, we identify a critical role for choline metabolism in driving IL-4 macrophage polarization and shaping the cellular immune response to intestinal helminth infection." (PMID 37747879, 2023). "In both cases, worm infections stimulated immune cells to secrete IL-4, which polarized macrophages and shifted the immune response from TH1 to TH2, which impaired control of viral infection in the gastrointestinal tract." (PMID 37789420, 2023). "IL-4 and IL-13 are produced during helminth infections, which in turn activates the IL-4R/STAT signalling pathway." (PMID 37705099, 2023). "Our foregoing observations in STAT6−/− BMT recipients also suggested that regulatory IL-4 production by recipients after helminth infection can act on recipient IL-4–responsive cell populations to regulate GVHD." (PMID 37294277, 2023). "Ang4, Clca1, and Retnlb are goblet-cell associated genes that are induced during immune responses, such as bacterial and helminth infections, and are typically stimulated by type 2 and 3 immune cytokines such as IL-4/IL-13 (type 2) and IL-22 (type 3)." (PMID 37869014, 2023). "Here, we have investigated the functional impact of IL-4 and helminth infection on myeloid responses to mycobacteria or the cord factor-based adjuvant TDB in vitro and in vivo." (PMID 36753434, 2023). "According to our results, recipient T cells can be reprogrammed or immune conditioned to activate their Th2 pathway, generate TGF-β, and establish a regulatory autocrine IL-4 or Th2 loop after helminth infection." (PMID 37294277, 2023). "In the present study, the Th2/anti-inflammatory cytokines, IL-4 and IL-5, were higher in the helminth infection and coinfection in vitro stimulations compared to the TB stimulation." (PMID 37513018, 2023). "During helminth infection in the lung and intestine, ILC2s produced IL4 and IL13 using a BATF-dependent mechanism in response to epithelial damage and contributed to the epithelial restoration." (PMID 37893107, 2023). "Our data suggest that such a restriction of Th2 bias to the spleen also applies to IL-4-producing T cells in both helminth infections." (PMID 36753434, 2023). "The importance of macrophage-specific metabolism for M[IL-4] activation in the context of helminth infection has previously been shown." (PMID 37747879, 2023). "Tuft cells respond to helminth infection by releasing IL-25, which drives the release of IL-5, IL-13, and IL-4 by activated ILC2s." (PMID 39816832, 2023). "Our main findings from these data seem to highlight that the metabolic responses of macrophages to helminth infection are likely a consequence of both activating signals (i.e. IL-4) and the state of differentiation from monocytic origin." (PMID 37699869, 2023). "Here, we investigated functional consequences of IL-4 and helminth infection on MINCLE-driven macrophage activation and Th1/Th17 adjuvanticity." (PMID 36753434, 2023). "SP-A and SP-D enhanced IL-4/IL-13-dependent M2 macrophage activation, promoting lung repair during helminth infection." (PMID 37234176, 2023). "Helminth infections induce a T helper-2 (Th-2) skewed immune responses characterized by interleukin 4 (IL-4), IL-5 and IL-13 cytokine responses and regulatory T cell responses with the production of IL-10 and tumor growth factor-β (TGF-β)." (PMID 36662839, 2023). "Type 2 cytokines like IL-4 are hallmarks of helminth infection and activate macrophages to limit immunopathology and mediate helminth clearance." (PMID 37747879, 2023).
helminth infection (continued). "AAMs are induced by IL-4-secreting memory Th2 cells in the context of helminth infections and were described to mediate protection not only during secondary Hpb infection but also during secondary infection with Nippostrongylus brasiliensis (Nb)." (PMID 37018382, 2023). "Overall, IL-4 signaling seems to protect against disease worsening in helminth infection and joint inflammation while it promotes resolution of inflammation in acute lung injury or myocardial infarction." (PMID 36809715, 2023). "The H. contortus AK upregulated IL-4 secretion to initiate the Th2 response that helps the host eliminate parasites; conversely, it induced Treg production to promote parasitic helminth infection." (PMID 36451837, 2022). "This is expected since helminth infections induce a polyclonal stimulation of IgE synthesis via IL‐4,22 giving rise to high serum total IgE." (PMID 35188279, 2022). "As expected in a helminth infection, the frequency and number of IL-4+ CD4+ Th2 cells increased in both the MLN and small intestine upon H. polygyrus infection." (PMID 35428872, 2022). "During helminth infections, IL-4 and IL-13 stimulate goblet cell hyperplasia, increasing mucin secretion which helps expel intestinal worms." (PMID 36569914, 2022). "In particular, activated basophils release IL-4, IL-13, and histamine and are known to be a source of IL-4 in parasitic helminth infections." (PMID 35970557, 2022). "An Il-4 CNS2 has been identified that is crucial for IL-4 expression, a cytokine responsible for IgG and IgE antibodies production by B cells, the defense against extracellular parasites, particularly helminthic infections, and allergic reactions." (PMID 35812386, 2022). "Helminth infection differentiates macrophages into M2 phenotype through increasing expression of IL-4 and maintaining the IL-4 signaling pathways (e.g. fatty acid oxidation, FAO and OXPHOS)." (PMID 35281054, 2022). "In the context of IL-4-inducing helminth infection, genetic ablation of phagocytic receptors, MerTK and AXL, leads to reduced proliferation of macrophages and induction of anti-inflammatory and tissue repair genes." (PMID 33668084, 2021). "IL-4Rα signaling is crucial for the accumulation of GATA3+ Tregs in the inflamed intestine during helminth infections; therefore we analyzed the Th2 cytokines IL-4, IL-5, and IL-13 secreted by LPMCs in the colon." (PMID 34336843, 2021). "Basically, helminthic infection activates Th2 cells that secrete IL-4, IL-5 and IL-13, then IL-4 stimulates B cells to produce helminth-specific Ig-E, which opsonize the helminths and promote binding to IL-5 activated eosinophils via FcεR." (PMID 34413850, 2021). "CD4+ Th2 cells producing IL-4, IL-5, and IL-13 direct cellular immunity in mucosal tissues to maintain barrier integrity after helminth infection." (PMID 34106992, 2021). "Th2 immune responses are characterized by IL-4 secretion, which acts as key mediator of humoral immunity to control helminth infection." (PMID 34022913, 2021). "In several helminth infections, IL-4, IL-13 and IL-5 producing Th2 cells are related to the most important effector mechanisms in adaptive pulmonary immunity against helminths." (PMID 34324507, 2021). "The immune environment in helminth infection is often characterized as T helper 2 (Th2) biased and involves the orchestration of cytokines (IL-4, IL-5, IL-13), antibodies, and regulatory cells." (PMID 33737927, 2021). "The requirement of IL-4 for protective responses is highly variable between different helminth infection models, which can also depend on the genetic background of the mice." (PMID 33983946, 2021). "The production and optimal affinity of these isotypes largely depends on the presence of IL-4-expressing Tfh cells in the context of helminth infection and IL-13-producing Tfh cells in the context of high-affinity IgE after allergen challenge." (PMID 34106992, 2021).
helminth infection (continued). "In contrast, Th2 cells are activated by IL-4 to produce cytokines such as IL-4, IL-5, and IL-10, and play important roles in the response to helminthic infections and B cell activation." (PMID 33532141, 2021). "Another relevant study showed that IL-4/13 collaborate with local tissue enhancers that amplify their response upon helminth infection." (PMID 33720008, 2021). "The host showed mainly the Th2 type of immune response against helminth infection, characterized by the secretion of cytokines, such as IL-4, IL-5 and IL-13." (PMID 34930417, 2021). "Helminth infections usually trigger a Th2 immune response in the host, by releasing cytokines such as IL-4, IL-5, IL-13 and IL-33." (PMID 34324507, 2021). "In type 2 cytokine-polarized environments such as helminth infection or in vivo IL-4 complex injection, RELMα expression is dramatically elevated reaching 100% expression by small and large peritoneal macrophages." (PMID 34349768, 2021). "IL-4 and IL-21 production by Tfh cells synergistically promotes the GC response during helminth infection." (PMID 33983946, 2021). "Other Th2-induced cytokines, such as IL-4, -6, -9, -10, and -13, also regulate mucin production, wheras IL-4 and -13 in worm infections increase goblet cell proliferation by activation of STAT-6 signaling." (PMID 34206809, 2021). "It has been recently described in mice that the ICAM-1-binding CD11a/CD18 heterodimer (LFA-1) controls Tfh generation and maintenance, and is involved in the development of IL-4 producing Tfh and Th2 cells during helminth infection." (PMID 33133070, 2020). "Helminth infections induce Th2 immune responses by expansion of innate immune cells such as eosinophils, M2 MACs, ILCs, and upregulation of cytokines such as IL-4, IL-5, and IL-13." (PMID 33613446, 2020). "The canonical cytokines of type 2 immune response, IL-4 and IL-13, involving helminth infection and allergic disorders, are the most important cytokines responsible for inducing alternative activation of macrophages." (PMID 32575834, 2020). "Second, while IL-4 is the dominant cytokine produced in lymphoid tissues during helminth infection, IL-13 appears to be more restricted to immune cells residing in mucosal tissues." (PMID 32793230, 2020). "IL4 has distinct functions in helminth infections but there is considerable redundancy with IL13, IL5 and IL9, whose contributions also vary among systems and parasite species/strains." (PMID 33226981, 2020). "Two examples: (i) during helminth infection IL-4 can expand and condition virtual memory CD8+ T cells (TVM cells) for more rapid CD8 responses against subsequent cognate antigen encounter." (PMID 33117371, 2020). "Although IL-4, IL-5, and IL-13 are responsible for the majority of type-2 immune hallmarks observed during helminth infection, IL-9 has been described to have additional effects on worm clearance." (PMID 32793230, 2020). "Basophils are granulocytes that produce type-2 cytokines including IL-4, IL-5, and IL-13 in addition to histamine, leukotrienes, and prostaglandins during degranulation as a result of helminth infection." (PMID 33193446, 2020). "This is expected as helminth infections would stimulate the production of protective cytokines, such as IL-4, which are responsible for the activation and expansion of the Th2 cells." (PMID 31449535, 2019). "In general, helminth infections commonly induce a strong Th2 response, which is orchestrated by many different cell types and characterised, among others, by the secretion of IL-4, IL-5 and IL-13." (PMID 31315623, 2019). "49: 1067–1081] uses a variety of transgenic murine strains to revise our understanding of the complexity of how these subsets undergo M(IL‐4) activation and participate in wound healing responses in helminth infection." (PMID 31267552, 2019). "The IL-4, IL-5, IL-13, are cytokines typically associated with a T helper 2 (TH2) response, the predominant protective immune response against helminthic infections." (PMID 30870421, 2019).